COL11A1 (collagen type XI alpha 1 chain)
Diseases named in the same sentence as COL11A1 in open-access papers (continued):
Sharing a sentence is not in itself a finding about the gene and the disease.
carpal tunnel syndrome (2 papers, 2022 to 2026). Entrapment of the median nerve in the wrist that is characterized by numbness, tingling and painful movement. "These included associations with genes involved in neurotransmitter signaling (HTR3A), immune function (HLA-DQB1, BCL11A), extracellular matrix remodeling (COL11A1, ADAMTS17, LOXL4), axon guidance and neural development (DCC, ETV1, NEGR1), and carpal tunnel syndrome (DIRC3)." (PMID 41518141, 2026).
chondrosarcoma (2 papers, 2021 to 2024). A malignant cartilaginous matrix-producing mesenchymal neoplasm arising from the bone and soft tissue. "Members from this group show in a later study that NF-YA also regulates the promoter region of COL11A1 in rat chondrosarcoma (RCS) as well as mouse pre-chondrocyte ATDC5 cells, and also show in another study that transcription factor Sp1 also regulates COL11A1 expression in rodent RCS cells." (PMID 33668097, 2021).
colorectal adenocarcinoma (2 papers, 2014 to 2022). The most common type of colorectal carcinoma. "Moreover, expression of the majority of the genes (CACNA1H, COL1A1, COL11A1, FZD8, NGFR, SFRP2, WNT2B, and WNT5A) was associated with the ‘mesenchymal’ CMS group 4 in the TCGA (The Cancer Genome Atlas) Colorectal Adenocarcinoma dataset." (PMID 35892888, 2022).
COVID-19 (2 papers, 2023). A disease caused by infection with severe acute respiratory syndrome coronavirus 2. "All represented terms showed 5 common genes between our ORF-A549 cells and COVID-19 lung biopsies (COL1A1, COL4A3, COL4A4, COL5A1 and COL11A1)." (PMID 37545510, 2023).
diabetes (2 papers, 2011 to 2021). "Interestingly, diabetes-related alterations of the extracellular matrix and adhesion molecules were varied; Pecam, Mmp10, Lamc1, Itgb7, Mmp9, and Timp4 were up-regulated, but Col11a1, Fn1, Admts2, and Itgav were down-regulated." (PMID 21984919, 2011).
glioblastoma (2 papers, 2011 to 2013). The most malignant astrocytic tumor (WHO grade IV). "The signature may indicate a non-fibroblastic transition, as occurs in glioblastoma, in which case collagen COL11A1 is not co-expressed with the other genes of the attractor." (PMID 23468608, 2013).
glioma (2 papers, 2022 to 2024). A benign or malignant brain and spinal cord tumor that arises from glial cells (astrocytes, oligodendrocytes, ependymal cells). "Although type XI collagen is a minor fibrillar collagen, collagen XI alpha 1 chain (COL11A1) expression has been found to be upregulated in a variety of human cancers including colorectal, esophagus, glioma, gastric, head and neck, lung, ovarian, pancreatic, salivary gland, and renal cancers." (PMID 35847935, 2022).
Intellectual disability (2 papers, 2017 to 2021). "COL22A1 and COL11A1 exhibit increased expression in the bone tissue and hippocampus of mice with some of the symptoms of Kleefstra Syndrome (developmental delay, hypotonia, and craniofacial abnormalities), which is often accompanied by autistic symptoms and intellectual disability in humans." (PMID 29045412, 2017).
invasive ductal carcinoma (2 papers, 2016 to 2022). "Compared with invasive lobular carcinoma, COL11A1 showed higher expression levels of COL11A1 in invasive ductal carcinoma tissues." (PMID 36160004, 2022). "Several studies reported that COL11A1 is overexpressed in invasive ductal carcinoma (IDC) of the breast relative to ductal carcinoma in situ (DCIS) in Spanish populations." (PMID 27857161, 2016).
lumbar disc degeneration (2 papers, 2015 to 2024). "It is interesting to note that Col11a1 mutations have been identified by genome-wide association studies for lower back pain and lumbar disc degeneration in some populations." (PMID 26779434, 2015).
lymphedema (2 papers, 2025). Excess fluid collection in tissues, causing swelling. "During follow-up validation, COL11A1 was found not to be differentially expressed between lymphedema and normal tissues, and was therefore excluded from further analysis." (PMID 40881699, 2025).
pancreatic adenocarcinoma (2 papers, 2022). "Further, FOXP4-AS1 exerts oncogenic activity in PAAD and COL11A1 as an immune infiltrates correlated prognosticator in pancreatic adenocarcinoma." (PMID 35033072, 2022).
salivary gland carcinoma (2 papers, 2022 to 2023). A carcinoma that arises from the major or minor salivary glands. "Although most studies showed that COL11A1 was mainly expressed in CAFs, yet COL11A1 was also found to be expressed in certain kind of tumor cells, such as the tumor cells of salivary gland cancer (SGC) with intercalated duct origin." (PMID 36744260, 2023).
Tinnitus (2 papers, 2024). Tinnitus is an auditory perception that can be described as the experience of sound, in the ear or in the head, in the absence of external acoustic stimulation. "In addition, a significant interaction was observed between greenness and genetic predisposition to tinnitus (including the MSRA and COL11A1 gene polymorphisms, and PRS for tinnitus)." (PMID 38445888, 2024).
acute lymphoblastic leukemia (1 paper, 2021). Leukemia with an acute onset, characterized by the presence of lymphoblasts in the bone marrow and the peripheral blood. "In stark contrast, it has been shown in hematological malignancies including Acute Myeloid Leukemia (AML), Chronic Lymphocytic Leukemia (CLL), B-Cell Acute Lymphoblastic Leukemia (B-ALL), and Diffuse Large B-cell Lymphoma (DLBCL) that COL11A1 overexpression is associated with better prognosis." (PMID 33668097, 2021).
adenomatous familial polyposis (1 paper, 2023). "Along the same line, and surprisingly, COL11A1 seems to be also overexpressed in colon polyps of patients with adenomatous familial polyposis via mutation in APC." (PMID 37760937, 2023).
adolescent idiopathic scoliosis (1 paper, 2024). A scoliosis with no known cause arising in adolescent. "(A) A heatmap of transcript per million (TPM) values of COL11A1, MMP14, and other published genes associated with adolescent idiopathic scoliosis (AIS)." (PMID 38277211, 2024).
aneurysmal disease (1 paper, 2019). "In this AAA gene list we identified previously AAA-associated genes COL11A1, ADIPOQ, and LPL, thus validating our approach as well as novel genes; CXCL13, SLC7A5, FDC-SP not previously linked to aneurysmal disease." (PMID 31683995, 2019).
aortic valve calcification (1 paper, 2022). "Among DEGs not related to humoral immunity many overlap with those already implicated in aortic valve calcification, these include TNC, PRG4, COL11A1, SMOC2, FN1, and OGN." (PMID 36437309, 2022).
cervical disc degeneration (1 paper, 2024). "COL11A1 CC genotype was significantly correlated with cervical disc degeneration." (PMID 39200631, 2024).
cervical squamous cell carcinoma (1 paper, 2023). A squamous cell carcinoma arising from the cervical epithelium. "POSTN + fibroblasts showed high expression levels of several ECM remodeling genes (MMP11, CTHRC1, COL1A1, COL1A2, COL3A1, COL10A1, and COL11A1) and enriched signatures of ECM, which were consistent with the previously reported matrix CAFs (mCAFs) in cervical squamous cell carcinoma (CESC)." (PMID 37833788, 2023).
dermatofibrosarcoma protuberans (1 paper, 2017). Dermatofibrosarcoma protuberans (DFSP) is a rare infiltrating soft tissue sarcoma, generally of low grade malignancy, arising from the dermis of the skin and characteristically associated with a specific chromosomal translocation t(17;22). "Many sarcomas are driven by gene fusions, such as COL11A1-PDGF that drives dermatofibrosarcoma protuberans (DFSP)." (PMID 29141020, 2017).
diabetic cardiomyopathy (1 paper, 2024). Diabetic cardiomyopathy is a disorder of the heart muscle in people with diabetes. "After the two exercise models, three genes related to diabetic cardiomyopathy overlapped: Col11a1, Pdk4, and Comp." (PMID 38547044, 2024).
dysplasia (1 paper, 2024). A usually neoplastic transformation of the cell, associated with altered architectural tissue patterns. "However, COL11A1 mutation can not only result in joint dysplasia, but fibro‐chondrogenesis as well." (PMID 38314968, 2024).
Ehlers-Danlos syndrome (1 paper, 2024). The Ehlers–Danlos syndromes (EDS) are a clinically and genetically heterogeneous group of heritable connective tissue disorders (HCTDs) characterized by joint hypermobility, skin hyperextensibility, and tissue fragility. "Blueprint Genetics Ehlers-Danlos Syndrome Panel (41 genes) identified three variants in our patient: two identical homozygous variants in AEBP1 c.2923del and a heterozygous variant in COL11A1 c.1160A>G." (PMID 38674395, 2024).
endometrial carcinoma (1 paper, 2022). A malignant tumor arising from the epithelium that lines the cavity of the uterine body. "Of note, tumour cells with staining for COL11A1 (TCCOL11A1) were detected in one OC as well as one endometrial carcinoma with a percentage of 5% and 70% of tumour cells, respectively." (PMID 34378164, 2022).
Hernia (1 paper, 2021). "Other authors have found a statistically significant association between SNV rs1676486 of the COL11A1 gene and hernia of the lumbar IVD in Asians (using the example of the Japanese and Chinese populations)." (PMID 34572492, 2021). "In addition, a decrease in the expression of the COL11A1 gene was associated with a hernia of the lumbar IVD and a higher degree of its degeneration." (PMID 34572492, 2021). "A statistically significant association was found between the SNV rs1676486 (c.4603C→T) of the COL11A1 gene and hernia of the lumbar IVD in Japanese patients with lower back pain." (PMID 34572492, 2021).
Hyperglycemia (1 paper, 2024). An increased concentration of glucose in the blood. "Additionally, hyperglycemia could activate the YAP/TAZ signaling pathway in cancer-associated fibroblasts to upregulate expression of fibronectin, fibroblast activation protein, COL1A1 and COL11A1, to enhance EMT and chemoresistance of PC." (PMID 38581008, 2024).
in situ carcinoma (1 paper, 2023). A malignant epithelial neoplasm which is confined to the epithelial layer without evidence of further tissue invasion. "Otherwise, COL11A1 expression was determined in the lesion that implies a greater diagnostic challenge, that is, in situ carcinomas settled on adenomatous polyps." (PMID 37760937, 2023).
intervertebral disc degeneration (1 paper, 2025). "There is less data on COL11A1 allele frequency in Western populations; however, meta-analyses confirm that rs1676486 is significantly associated with intervertebral disc degeneration across studies." (PMID 40649133, 2025).
intraductal papilloma (1 paper, 2015). An intraluminal papillary epithelial neoplasm arising within the ducts. "We analyzed the correlation between expression of pro-COL11A1 in intraductal papilloma and their risk of malignant recurrence." (PMID 26448946, 2015). "COL11A1 expression in fibroblast surrounding central fibrovascular stalks of intraductal papillomas can predict future malignant relapse with a sensitivity of 91%." (PMID 26448946, 2015). "The present work demonstrates that the presence of COL11A1 in the stroma of breast intraductal papillomas could be a potential marker of malignant behavior." (PMID 26448946, 2015). "COL11A1 is not present in benign lesions so we thought it can be a predictable marker for malign behavior of intraductal papilloma." (PMID 26448946, 2015).
leiomyoma (1 paper, 2023). A well-circumscribed benign smooth muscle neoplasm characterized by the presence of spindle cells with cigar-shaped nuclei, interlacing fascicles, and a whorled pattern. "Several other genes, although upregulated in non-mutated samples, showed a greater magnitude of increase in expression in the mutated leiomyoma group, including FN1, DCX, and COL11A1." (PMID 36835153, 2023).
leukoplakia (1 paper, 2025). A white patch or plaque on a mucous membrane that cannot be characterized clinically or pathologically as any other disease. "Although our analysis compared OSCC to BC samples, 19 significant genes overlapped with Farah and Fox’s 47 differentially expressed genes (DEGs), including the upregulation of ODC1 and LCN2 and the downregulation of COL1A1, COL11A1, and STAC2 in dysplastic leukoplakia samples." (PMID 40650045, 2025).
liver cancer (1 paper, 2025). An epithelial or non-epithelial malignant neoplasm that arises from the liver. "We also find increased expression of myofibroblasts and fibrosis markers (PDGFRB, COL1A1, COL3A1, COL11A1) and early liver cancer markers (GPC3 and MUC1)." (PMID 41065540, 2025).
lung neoplasm (1 paper, 2021). A benign or malignant, primary or metastatic neoplasm involving the lungs. "Cancers displaying the highest frequency of collagen gene family mutations independent of COL11A1 included cutaneous, gastrointestinal (esophageal, colorectal), urogenital (cervical, bladder), and lung neoplasms." (PMID 34584216, 2021).
lymphoma (1 paper, 2022). A malignant (clonal) proliferation of B- lymphocytes or T- lymphocytes which involves the lymph nodes, bone marrow and/or extranodal sites. "For the first time, we used RNA in-situ hybridization to systematically identify the cells that produce COL11A1 in the ten most prevalent carcinoma types, lymphomas (n = 275) and corresponding normal tissue (n = 55; panCancer cohort)." (PMID 34378164, 2022).
mesenchymal neoplasms (1 paper, 2022). "Even though COL11A1 production by tumour cells has been reported for mesenchymal neoplasms, we are the first to report this mechanism in carcinomas." (PMID 34378164, 2022).
microtia (1 paper, 2017). "Thus we suggest that the two genes, COL4A4 and COL11A1, may be strongly involved in the mechanism of microtia and are worth exploring in the context of the pathogenesis of microtia." (PMID 28968992, 2017).
papillary carcinoma (1 paper, 2015). A malignant epithelial neoplasm characterized by a papillary growth pattern. "All five encapsulated papillary carcinoma were positive for COL11A1 staining." (PMID 26448946, 2015).
papilloma (1 paper, 2015). A benign epithelial neoplasm that projects above the surrounding epithelial surface and consists of villous or arborescent outgrowths of fibrovascular stroma. "Immunohistochemistry of pro-COL11A1 was performed in 62 samples of intraductal papilloma." (PMID 26448946, 2015). "Nonparametric Fisher exact test was performed, using SPSS 20 suite, to analyze difference of COL11A1 expression between intraductal papilloma with or without malignant relapse." (PMID 26448946, 2015). "Pro-COL11A1 staining showed sensitivity of 91% and a specificity of 67% when compared intraductal papilloma malignant relapsed samples with those not recurrent." (PMID 26448946, 2015). "In any case, the absence of COL11A1 in a biopsy can predict with a high probability that an intraductal papilloma will present a benign behavior since it presents a recurrence HR value of 0.0793 (0.02–0.26), although changing in therapeutic behavior seems complicated without further studies." (PMID 26448946, 2015).
periodontitis (1 paper, 2025). An acute or chronic inflammatory process that affects the tissues that surround and support the teeth. "Previous studies have reported heterogeneity in gingival fibroblasts in periodontal tissues, with four subsets significantly altered in periodontitis: Fib 1.1 (CXCL1, CXCL2, CXCL13); Fib 1.2 (APCDD1, IGFBP2, MRPS6); Fib 1.3 (APOD, GSN, CFD); and Fib 1.4 (TIMP3, ASPN, COL11A1)." (PMID 40801798, 2025).
pneumococcal meningitis (1 paper, 2016). An acute purulent infection of the meninges and subarachnoid space caused by Streptococcus pneumoniae, most prevalent in children and adults over the age of 60. "We found one gene significantly associated when looking for associations between multiple common and rare variants with pneumococcal meningitis susceptibility, namely the COL11A1 gene." (PMID 27389768, 2016). "We found a marginally significant association of the COL11A1 gene with pneumococcal meningitis susceptibility." (PMID 27389768, 2016). "The sequence kernel association test (SKAT) tests for associations between multiple variants in a gene region and pneumococcal meningitis susceptibility yielded one significant associated gene namely COL11A1 (p = 1.03 × 10−7)." (PMID 27389768, 2016). "The association of the COL11A1 gene could indicate that differences in the extracellular matrix or anatomical defects can alter the susceptibility of pneumococcal meningitis." (PMID 27389768, 2016). "Our strongest signals associated with susceptibility to pneumococcal meningitis were rs139064549 on chromosome 1 in the COL11A1 gene (p = 1.51 × 10−6; G allele OR 3.21 [95% CI 2.05–5.02]) and rs9309464 in the EXOC6B gene on chromosome 2 (p = 6.01 × 10−5; G allele OR 0.66 [95% CI 0.54–0.81])." (PMID 27389768, 2016).
primary closed-angle glaucoma (1 paper, 2019). "Mutations in collagen type XI alpha 1 chain (COL11A1) and pleckstrin homology domain containing A7 (PLEKHA7) genes were designated as crucially important risk factors for the development of primary closed-angle glaucoma." (PMID 31949441, 2019).
renal carcinoma (1 paper, 2022). A carcinoma arising from the epithelium of the renal parenchyma or the renal pelvis. "TGF-β1 has been found to regulate COL11A1 in colorectal, pancreatic, and renal cancers, thereby promoting cancer proliferation and invasion." (PMID 35847935, 2022).
retinal dystrophies (1 paper, 2022). "Ten families had variants in genes related to a syndromic disease with retinal dystrophy (COL9A1, CEP290, PCDH15, LRP5, PEX1, CFH, COL2A1 and COL11A1)." (PMID 35457050, 2022).
salivary duct carcinoma (1 paper, 2022). An aggressive, high grade adenocarcinoma that arises from the salivary glands. "We report that colon, breast and salivary duct carcinomas are highly infiltrated by COL11A1 positive CAFs (CAFsCOL11A1) and might thus be promising candidates for antidesmoplastic or COL11A1-targeted therapies." (PMID 34378164, 2022).
sarcoidosis (1 paper, 2025). Sarcoidosis is a multisystemic disorder of unknown cause characterized by the formation of immune granulomas in involved organs. "However, unlike NL and NXG, COL4A4, COL6A6, and COL11A1 were not significantly upregulated in sarcoidosis fibroblasts, and CCL5 was only modestly upregulated." (PMID 39989459, 2025).
Sciatica (1 paper, 2012). Pain in the lower back and hip radiating in the distribution of the sciatic nerve. "A Japanese study found an association between COL11A1 rs1676486 T-allele and LDH characterized by sciatica." (PMID 23185509, 2012).
scleroderma (1 paper, 2021). Scleroderma is a rare autoimmune connective tissue disorder characterized by abnormal hardening of the skin and, sometimes, other organs. "Elevated COL11A1 was also observed in scleroderma skin, another condition with extensive fibroblast activation." (PMID 33932142, 2021).
stomach adenocarcinoma (1 paper, 2022). "We also investigated the impact of CAF markers highly clustered with COL1A1 and COL5A1 in correlation analysis, namely THBS2, FAP, INHBA, S100A4, COL11A1, or MMP11, on the outcome of CAF infiltration in stomach adenocarcinoma." (PMID 35739492, 2022).
systemic sclerosis (1 paper, 2025). A chronic disorder, possibly autoimmune, marked by excessive production of collagen which results in hardening and thickening of body tissues. "Also, the upregulation of COL4A4, COL8A1, and COL11A1 in systemic sclerosis fibroblasts was not nearly as strong as that observed in NL fibroblasts." (PMID 39989459, 2025).
testicular germ cell tumor (1 paper, 2024). A germ cell tumor arising from the testis. "The expression of COL11A1 is negatively correlated with most immunoinhibitors and immunostimulators in testicular germ cell tumors and uveal melanoma." (PMID 38649961, 2024).